CLU (clusterin)
Diseases named in the same sentence as CLU in open-access papers (continued):
Sharing a sentence is not in itself a finding about the gene and the disease.
tumor (continued). "Evaluation of CLU and LC3II protein levels from these PC3 tumours confirmed that OGX-011 suppressed autophagy activation associated with paclitaxel." (PMID 25503391, 2014). "We demonstrate, for the first time, that CLU inhibition abrogates the heat shock response and synergistically potentiates the cytotoxic activity of ZOL directly on tumor cells, thus, preventing emergence of resistance." (PMID 25138053, 2014). "We also defined the functional interactions between GRP78 and CLU in HCC cell lines and further determined the correlation between CLU and GRP78 expressions in an orthotopic xenograft tumor model and clinical HCC specimens." (PMID 23457489, 2013). "The effect of CLU knockdown on GRP78 expression and cell apoptosis in HCC tumors were further determined in orthotopic xenograft tumor model." (PMID 23457489, 2013). "Our previous analysis demonstrated differences in expression between tumours from survivors and tumours from deceased patients, including four cancer-related genes, ITGB3, CLU, CAPG, and PRAME." (PMID 19775429, 2009). "The expression of CLU, ITGB3, CAPG, and PRAME was investigated to study differences in expression levels between tumours from survivors and tumours from deceased patients." (PMID 19775429, 2009). "The proteins CLU, ITGB3, CAPG, and PRAME were examined with western blot for semiquantitative measurements of each protein in 98 tumours." (PMID 19775429, 2009). "We have hereby opened up a new field of investigation into biomarkers of this tumor type and have identified two promising candidate genes: LGALS4 and CLU." (PMID 19903339, 2009). "Clusterin (CLU), a secreted chaperone-like protein, is upregulated in BC and metastatic tissue; however, its functional contribution to tumor aggressiveness remains unclear." (PMID 41751858, 2026). "Interestingly, in the CRLM-CA subgroup, clusterin was primarily observed in hepatocytes surrounding the tumor cells, highlighting an interaction between CRLM and surrounding tumor microenvironment." (PMID 40617497, 2025). "Fourth, we did not explore the tumor-suppressing or tumor-promoting effects of clusterin, which emerged as a key driver of the effects of EVSASC on cardiomyocytes." (PMID 40671119, 2025). "Moreover, upregulation of CLU expression combined with L1CAM mediated signalling, a marker of tumour cells with metastatic potential, within LS174T CRC tumour cells results in substantial metastasis formation within the liver and spleen after transplantation." (PMID 38319453, 2024). "Additionally, the silencing of CLU and PRKD3, through the CLU silencer OGX-011 and the PRKDs inhibitor CRT0066101 suppressed tumor growth both in vitro and in vivo." (PMID 38473804, 2024). "Clusterin (CLU) is expressed in various tissues of the human body and is a 449 amino acid, heterodimeric glycoprotein with a plausible role in the regeneration, migration, and antiapoptosis of tumor cells." (PMID 36267311, 2022). "The results indicated that CLU expression levels differed significantly among the 21 types of tumor tissues and non-tumor tissues that matched the tumor tissues." (PMID 36685863, 2022). "It speculated that the upregulated expression of CLU, GNAS, and PKM may inhibit the occurrence of tumor in the early stage, while the expression decreased in the late-stage promotes the development of tumor." (PMID 33299887, 2020). "In summary, these results demonstrated that CLU, GNAS, and PKM are differentially expressed in the serum of MF patients and normal subjects, which may inhibit the occurrence and development of tumor directly/indirectly." (PMID 33299887, 2020). "Other soluble regulators as clusterin, C1 inhibitor, factor I and C4b-binding protein (C4BP) are secreted by tumor cells into the tumor milieu and could also be detected in the circulation." (PMID 31001273, 2019). "When CLUKO mice were crossed with TRAMP to obtain TRAMP/CLUKO mice, we found that tumor spreading and metastases occurred earlier in animals lacking CLU expression." (PMID 31885575, 2019).
tumor (continued). "In this context, Clusterin (CLU) is a new pleiotropic factor potentially involved in the stimulation of inflammatory cytokines such as IL6 and lipid metabolism, cell differentiation, tissue remodeling and neoplastic diseases." (PMID 30967152, 2019). "The data also show that the level of serum clusterin have no significance difference in different lymph node status patients (p = 0.8142), as well as tumor size (p = 0.4066)." (PMID 28954633, 2017). "Moreover, increased staining of CLU in the cytoplasm of tumor cells was detected, which indicated CUL is important for tumor cell surviving." (PMID 29296216, 2017). "The aim of this study was to prospectively validate a gene expression panel (composed of GAPDH, VIL1, CLU, TIMP1, TLN1, LOXL3 and ZEB2) for detecting circulating tumor cells (CTCs) as prognostic and predictive tool in blood samples from 94 metastatic CRC (mCRC) patients." (PMID 28608814, 2017). "These suggest that DNP may increase MMP-9 and VEGF expression through regulation of CLU, remodeling extracellular matrix (ECM) and promoting tumor angiogenesis, participate in NPC metastasis." (PMID 26716898, 2016). "No significant decreases in tumor volume were observed with clusterin silencing and DDP monotherapies, alone." (PMID 25884382, 2015). "Proteomic analysis of MDCKYBX1 tumour xenografts revealed 428 proteins identified in MDCKYBX1 tumour xenografts, and EMT markers (VIM, FN1 and S100A4) and proteins involved in cancer progression (H-Ras and CLU) were identified." (PMID 25980435, 2015). "It is not clear why clusterin play contradictory functions, such as cell survival, tumor progression, treatment resistance or cell apoptosis." (PMID 26293319, 2015). "We found no significant decreases in tumor volume with clusterin silencing and DDP monotherapies (P > 0.05)." (PMID 25884382, 2015). "Other factors, such as gender, age, tumor location, lymph node yield, and clusterin concentration, were not significantly correlated with prognosis in ESCC patients." (PMID 25574066, 2014). "Furthermore, we also found that down-regulation of CLU and GRP78 was correlated with cleavage of PARP in tumor tissues." (PMID 23457489, 2013). "However, earlier studies have reported CLU as down-regulated and CAPG and PRAME as up-regulated in advanced carcinomas compared to early tumours or normal tissue." (PMID 19775429, 2009). "In contrast to normal mucosa, CLU was found to be absent in tumors except in one high-grade non-ITAC tumor (Patient P11) where there was a diffuse cytoplasmic staining." (PMID 19903339, 2009). "Firstly, while ERBB2 and CLU expression were found to be elevated in tumor tissues compared to non-tumor tissues, their expressions were lower in the high-risk group compared to the low-risk group, indicating an inconsistency between prognostic trend and expression pattern." (PMID 39744560, 2025). "Notably, tumours originating from the midgut were not included in the cases studied, suggesting that the CLU expression level was potentially lower in NET G3 from the midgut than in those originating elsewhere." (PMID 39484039, 2024). "Moreover, upregulation of genes CLU, NNMT, and S100A6, which are known to promote RCC cell proliferation and metastasis, were found exclusively in the tumor compartment of Endo-2 and could indicate a supportive role of these cells to RCC progression." (PMID 36180422, 2022). "However, higher expression of CLU in tumor tissues leads to a worse prognosis of cancer in these studies, and we believe that this CLU gene is sCLU, which has a negative effect on cancer prognosis." (PMID 36685863, 2022). "Since it was hypothesized that high CLU expression levels may suppress tumor progression at early, but not late, stages of carcinogenesis, we then investigated the functional implication of CLU OE in cancer." (PMID 33744871, 2021).
tumor (continued). "In addition, we show that CLU, MMP-9 and VEGF can also be detected at the NPC tissues, which could open new avenues for both the tumor metastasis and the development of novel immunotherapeutic strategies in NPC." (PMID 26716898, 2016). "In addition, CLU expression levels correlated significantly with tumor grade and multiplicity but not with tumor size." (PMID 24156019, 2013). "It showed AS clusterin ODN alone did not have significant effect on the tumor growth." (PMID 21609464, 2011). "Expression patterns of clusterin at different stages indicate that this protein functions in the maintenance and/or progression of tumors, but it is not clear whether it plays a role in tumor establishment." (PMID 33356806, 2021). "Thus, BHLHE40-mediated tumor suppression can be traced to inhibition of oncogenic factors such as STAT1, whereas BHLHE40-mediated promotion of tumor progression may be traced to the activation of the PI3K/Akt/mTOR pathway and the upregulation of pro-survival factors such as survivin and clusterin." (PMID 32577154, 2020). "However, HMGB1 could not protect anti-sense CLU-transfected DU145 tumor cells from DTX cytotoxicity, Thus, sCLU induction by HMGB1 mediates protection from DTX cytotoxity, resulting in drug resistance." (PMID 26469759, 2015). "In contrast to previous studies, we did not observe an increase in afamin, clusterin, VDBP, or A1AT in the serum of tumor-bearing gp130Y757F mice versus wild-type in either early- or late-stage diseases." (PMID 38542101, 2024). "The tumor is negative for EMA, cytokeratin 7, cytokeratin 20, chromogranin A, synaptophysin, S-100 protein, HMB-45, desmin, SMA, EBV, CD117, DOG1, CD23, CD21, clusterin, MDM2, CD34, D240, and ERG." (PMID 31623602, 2019). "A significant difference in expression between tumours from survivors and tumours from deceased patients was detected for ITGB3 (p = 0.005), but not for the other proteins, CLU (p = 0.15), PRAME (p = 0.62), and CAPG (p = 0.24)." (PMID 19775429, 2009). "Additionally, PTC patients with tumor extrathyroidal extension had significantly lower PROS1, CLU, and LRG1 IHC scores compared to patients without extrathyroidal extension (P = .001, P = .001, and P = .001, respectively)." (PMID 40797389, 2025). "In this case, expression of EMA, clusterin, or CD56 in tumor cells may help to support a diagnosis of ALK negative ALCL, as the staining of these markers are known to be absent in HL." (PMID 27612448, 2016).
cancer (183 papers, 2007 to 2026). A tumor composed of atypical neoplastic, often pleomorphic cells that invade other tissues. "Clusterin is one of the many known proteins implicated in cancer chemoresistance, which hinders the effectiveness of chemotherapy." (PMID 40563890, 2025). "Clusterin is a protein implicated in cancer chemoresistance, a significant obstacle in effective chemotherapy." (PMID 40563890, 2025). "Dysregulation of CLU has been linked to various pathological conditions, including neurodegenerative diseases and cancer." (PMID 39627493, 2025). "CLU overexpression has been associated with the promotion of tumorigenesis and resistance to chemotherapy in various types of cancer, including breast and prostate." (PMID 38667280, 2024). "Upregulated expression of CLU has been linked to increased chemoresistance in multiple cancer types including the breast, lung, prostate, bladder, liver, pancreatic, ovarian, cervical, melanoma and osteosarcoma." (PMID 38319453, 2024). "Another perspective to look at concerning CLU protein association with cancer is the level of CLU methylation." (PMID 37239129, 2023). "CLU expression has also been associated with worse survival in cancer patients in many recent studies, including KIRC and LIHC." (PMID 36685863, 2022). "CLU, which performs a number of different functions and has also been associated with neurodegenerative diseases and cancer, also acts as a chaperone outside the cell and facilitates the extracellular clearance of misfolded proteins." (PMID 35435317, 2022). "Through this function, CLU is implicated in many oxidative stress-related diseases, including neurodegenerative diseases, cancer, inflammatory diseases and aging." (PMID 35203598, 2022). "Taken together these findings further support the notion that BRCA mutations in the cancer cells lead to a stromal shift from TGFβ induced SMA+ myofibroblasts to HSF1-induced CLU+ fibroblasts." (PMID 36316305, 2022). "Structural identification and absolute quantitation of cancer-associated intact clusterin glycopeptides." (PMID 35975084, 2022). "CLU gene deletions were found in virtually all malignancies and were associated with the prognosis of most cancer patients." (PMID 36685863, 2022). "CLU expression was significantly associated with immunological infiltration and checkpoint markers in several cancers." (PMID 36685863, 2022). "CLU is also implicated in all stages of cancer, i.e., progression, promotion, metastasis and chemoresistance acquisition." (PMID 33744871, 2021). "This suggests the association between the cancer cell and Clusterin protein level of the immune cell." (PMID 34290294, 2021). "Clusterin (CLU) is implicated to play important oncogenic roles in cancer via promoting various downstream oncogenic pathways." (PMID 33643800, 2021). "The intravenous dispensation of Pc 4 and light application to animals carrying UVB radiation-caused skin papillomas provoked an augmentation of clusterin production, peaking at 24 h after the therapy, when the cancer reduction was evident." (PMID 32455998, 2020). "Clusterin (CLU) is a stress-associated cytoprotective protein up-regulated by various apoptotic triggers in many cancers and confers treatment resistance when overexpressed." (PMID 33170151, 2020). "Despite these co-associations, mechanisms linking CLU and autophagy activation to stress tolerance and cancer treatment resistance are undefined." (PMID 25503391, 2014). "Quantitative PCR-analyses revealed the expression of four different stress-inducible CLU mRNA variants in non-cancer and cancer cell lines." (PMID 24073260, 2013). "Previous reports have implicated CLU up-regulation as a general defense mechanism of cancer cells toward cytostatic drugs." (PMID 22417809, 2012). "In recent years, clusterin has been considered a potential diagnostic and prognostic biomarker for several human cancers." (PMID 22390717, 2012). "Abnormal CLU expression is associated with cancer development and progression." (PMID 39905539, 2025).
cancer (continued). "Aberrant CLU expression has been associated with apoptosis in several cancers." (PMID 38535120, 2024). "In different cancer types, CLU overexpression has been associated with metastasis." (PMID 38667280, 2024). "Given the diverse regulatory pathways governed by CLU in cancer progression and the demonstrated survival benefits associated with its inhibition across different cancer types, CLU emerges as a promising therapeutic target for the development of more efficacious agents and targeted therapies." (PMID 38667280, 2024). "The data obtained so far indicate that the upregulation of CLU could be one of the main risk factors for aging, cancer, and neurodegenerative disorders." (PMID 39253532, 2024). "Furthermore, it was noted that the localization of clusterin within cells varied from the nucleus in healthy tissues to the cytoplasm in malignant tumors, which has been linked to the disease’s status." (PMID 37834086, 2023). "Specifically, CLU has been shown to play a role in the antiapoptotic capacities, the enhancement of treatment resistance, and the induction of epithelial-mesenchymal transition, all of which are associated with cancer metastasis." (PMID 36595996, 2022). "Chemical and enzymatic synthesis of cancer-relevant clusterin glycopeptide variants." (PMID 35975084, 2022). "The detection was achieved through the binding reaction between the antibody and varying concentrations of Clusterin antigen from 1 to 100 pg/mL, as well as specificity tests using human chorionic gonadotropin (hCG), a glycoprotein risk biomarker of certain cancers." (PMID 33869287, 2021). "The protein encoded by CLU is a secreted chaperone that may be involved in several basic biological events, such as cancer initiation and progression, and neurodegenerative disorders." (PMID 33521130, 2021). "CLU is nearly ubiquitously expressed in different tissues and associated with regulation of cell survival, migration/invasion, differentiation, cellular stress responses, and resistance to cancer therapy." (PMID 28902909, 2017). "Previous studies have also linked CLU expression with induction and progression of many cancers." (PMID 25138053, 2014). "A growing enthusiasm for therapeutic modulation of this proteostasis network highlights Hsp's and CLU as rational targets because of their multifunctional roles in signaling and transcriptional networks associated with cancer progression and treatment resistance." (PMID 25138053, 2014). "Several anti-cancer agents could activate ER stress, thus increasing CLU expression level, which may cause an acquired treatment-resistant phenotype." (PMID 23457489, 2013). "In addition, we investigated whether a correlation exists between a mutation in the CLU gene and a worse prognosis for patients’ clinical survival in several cancer types." (PMID 36685863, 2022). "Overall, our results indicate that CLU could be involved in gastrin-induced pro-survival signaling and remodeling of the oxyntic mucosa; and might therefore influence both gastric homeostasis and cancer risk." (PMID 28902909, 2017). "Beyond its canonical chaperone activity, CLU is involved in several biological processes, including cell survival, apoptosis, tissue remodeling, inflammation and cancer progression." (PMID 42279373, 2026). "In parallel, several cancer studies have shown that silencing CLU leads to cell proliferation arrest, for example, in renal cell carcinomas, human breast cancer cells, lung cancer, and osteosarcoma." (PMID 39627493, 2025). "The novelty of CLU silencing in cancer therapy lies in its ability to target the cellular mechanisms underlying both the treatment resistance and metastatic potential of tumors, offering a strategy that goes beyond traditional chemotherapy." (PMID 40573993, 2025). "CLU exhibits heightened expression across various cancers, including prostate, breast, and lung cancers." (PMID 40573993, 2025).